PAK1 (p21 (RAC1) activated kinase 1)
Diseases named in the same sentence as PAK1 in open-access papers (continued):
Sharing a sentence is not in itself a finding about the gene and the disease.
adenocarcinoma (5 papers, 2013 to 2025). A common cancer characterized by the presence of malignant glandular cells. "The PAK1 and phospho-PAK1 levels were elevated in HCC827 (EGFR-mutated adenocarcinoma cell line) cells compared to those in A549 (EGFR wild-type cell line) or BEAS-2B (normal bronchial epithelial cell line) cells." (PMID 33261184, 2020). "A step-wise increase in PAK1 levels was noted from paired normal epithelium, to atypical hyperplasia and adenocarcinoma." (PMID 24236193, 2013).
cardiac disease (5 papers, 2015 to 2025). "PAK1 mediates the phosphorylation of hypertrophy and/or arrhythmia-related proteins and plays important roles in cardiac diseases." (PMID 33796531, 2021). "Thus, Pak1 may thus offer a novel therapeutic target for modulation of Ca2+ handling in cardiac disease conditions." (PMID 25852566, 2015). "Moreover, Rac1 and its effectors have important roles in cardiomyocyte electrophysiology and arrhythmogenesis and therapeutic approaches directly targeting Rac1, NOX2, PAK1, or apoptosis signal-regulating kinase 1 (ASK1) have shown promise in preclinical models of cardiac disease." (PMID 41333012, 2025).
myopathy (3 papers, 2019 to 2022). A disease of the muscle in which the muscle fibers do not function properly. "Conditional loss of Pak1 and Pak2 in mice resulted in an age-dependent myopathy with similarity to mice and humans with CHKβ deficiency." (PMID 30791960, 2019). "Conditional mutagenesis is required in such cases; a situation similar to Pak1/2 is seen with mutation of Mtor, which is early embryonic lethal when removed from the germline but results in myopathy when removed selectively from skeletal muscle." (PMID 30791960, 2019). "Loss of both Pak1 and Pak2 in the muscle lineage is required to produce myopathy, and germline mutations in Pak2 result in early embryonic lethality." (PMID 30791960, 2019). "Moreover, those PAK1: PAK2 double KO mice exhibited myopathy with significant alterations in mitochondrial morphology, complicating interpretations." (PMID 35222279, 2022). "Although megaconial mitochondria are a distinguishing characteristic of both Chkb/CHKB and Pak1/2 deficiency, it is not clear whether they are the cause of the myopathy or a consequence of a different, underlying molecular and cellular defect." (PMID 30791960, 2019). "Here we report that mice lacking Pak1 and Pak2 conditionally in the skeletal muscle lineage develop a late-onset myopathy, characterized by the presence of megaconial mitochondria." (PMID 30791960, 2019). "We report here that mice lacking Pak1 and Pak2 in the skeletal muscle lineage develop a late-onset myopathy." (PMID 30791960, 2019).
metabolic disease (2 papers, 2020 to 2025). A congenital disorder (due to inherited enzyme abnormality) or acquired (due to failure of a metabolically important organ) disorder resulting from an abnormal metabolic process. "Altogether, these mechanisms may contribute to overall metabolic health, potentially exacerbating metabolic disorders when Pak1 signaling is impaired." (PMID 40065530, 2025). "Understanding how different exercise intensities affect molecular mechanisms such as Rac1 or PAK1 expression may reveal new therapeutic targets to treat patients with metabolic diseases." (PMID 33329033, 2020).
brain disorder (1 paper, 2016). A disease affecting the brain or part of the brain. "Future studies are needed to determine if such PAK1-targeting drugs could be useful for restoring excitatory and inhibitory balance in brain diseases or for treating other diseases involving the PAK proteins." (PMID 27296803, 2016).
colorectal (1 paper, 2017). "It has been recently shown that the activity of pro-survival factors downstream of CDC42, such as PAK1 is increased in CDC42-driven colorectal tumorigenesis and these cascade pathways can regulate transcription through transcription factors like NFκB and STAT3." (PMID 28460460, 2017).
hematological cancers (1 paper, 2023). "The importance of PAK1 in hematological cancers also has started to emerge." (PMID 37190165, 2023).
vascular disorder (1 paper, 2025). A general term used to describe any disease affecting blood vessels]. "We subsequently speculated that Nox1-regulated PAK1 is involved in vascular disorders." (PMID 39721498, 2025).
PAK1 also shares sentences with these, for which no sentence is quoted: neurological diseases (5 papers); asthma (3); chronic myeloid leukemia (3); infectious disease (3); speech delay (3); acute pancreatitis (2); adenoma (2); Arrhythmia (2); bipolar disorder (2); flu (2); Hydrocephalus (2); invasive carcinoma (2); malaria (2); microcephaly (2); tongue squamous cell carcinoma (2); uveal melanoma (2); abdominal aortic aneurysm (1); AIDS (1); amyotrophic lateral sclerosis (1); anxiety disorder (1); Ataxia (1); atrial tachycardia (1); bacterial infection (1); basal cell carcinoma (1); benign prostate hyperplasia (1); bone tumour (1); bronchioloalveolar carcinoma (1); cerebrovascular diseases (1); cervical squamous cell carcinoma (1); clear cell carcinoma (1).
A further 58 diseases each share a sentence with PAK1 in 1 paper.